SHANK3 (SH3 and multiple ankyrin repeat domains 3)
Diseases named in the same sentence as SHANK3 in open-access papers (continued):
Sharing a sentence is not in itself a finding about the gene and the disease.
SHANK3 also shares sentences with these, for which no sentence is quoted: genetic disorder (10 papers); neurodegenerative disease (3); autoimmune encephalitis (2); Kabuki syndrome (2); Kleefstra syndrome (2); language delay (2); Learning disabilities (2); Macrocephaly (2); microcephaly (2); neurofibromatosis (2); primary ciliary dyskinesia (2); type II diabetes (2); alcohol dependence (1); alcohol use disorders (1); alcohol withdrawal syndrome (1); amnesia (1); Anorexia (1); Aortic Valve Disease 1 (1); Aphasia (1); asthma (1); Atypical absence seizure (1); bacterial infections (1); behavioural disorders (1); Brain Trauma (1); cellulitis (1); channelopathy (1); ciliopathies (1); Cirrhosis (1); cocaine use disorder (1); colorectal cancer (1).
A further 46 diseases each share a sentence with SHANK3 in 1 paper.